TRAPPC9 (trafficking protein particle complex subunit 9)
Diseases named in the same sentence as TRAPPC9 in open-access papers (continued):
Sharing a sentence is not in itself a finding about the gene and the disease.
Obesity (14 papers, 2019 to 2024). Accumulation of substantial excess body fat. "Based on these observations, Trappc9 deficiency should hamper obesity development, as blunting NF-κB activation abates the development of obesity." (PMID 38889014, 2024). "We found that Trappc9-deficient mice presented with systemic glucose homeostatic disturbance, obesity, and NAFLD, which were relieved upon chronic treatment combining dopamine receptor D2 (DRD2) agonist quinpirole and DRD1 antagonist SCH23390." (PMID 38889014, 2024). "Along with prior findings that Trappc9 ablation dampens Rab11 activation and reduces dendritic spines, our studies support a model for the onset of obesity triggered by Trappc9 deficiency." (PMID 38889014, 2024). "Our study suggests that Trappc9 loss of function causes obesity and NAFLD by perturbing dopaminergic synapse formation." (PMID 38889014, 2024). "Our study suggests that Trappc9 gene mutations trigger the development of obesity by reducing dopamine synapse formation and provides a potential treatment." (PMID 38889014, 2024). "Trappc9 mice with only the maternal allele mutated appear overweight, whereas mice with only the paternal allele mutated are normal, indicating that obesity development in Trappc9-KO mice involves a loss of function mainly in the brain." (PMID 38889014, 2024). "Having demonstrated that Trappc9-KO mice develop obesity and NAFLD, we then looked for the underlying mechanisms." (PMID 38889014, 2024). "Our study suggests that Trappc9 loss of function causes obesity and NAFLD by constraining dopamine synapse formation." (PMID 38889014, 2024). "Over half of the patients with TRAPPC9 mutations are reported to present different degrees of obesity." (PMID 35865874, 2022). "Based on a single case, this suggests an essential role for TRAPPC9 in normal functioning of the brain feeding circuitry, with deficiency leading to hyperphagia and obesity in human." (PMID 32877400, 2020). "Reports to date have provided only limited insights into the impact of TRAPPC9 deficiency on energy balance and body composition, although obesity is frequently noted." (PMID 32877400, 2020). "On the contrary, Trappc9 deficiency results in obesity in both humans and mice." (PMID 38889014, 2024). "Loss-of-function mutations of the gene encoding the trafficking protein particle complex subunit 9 (Trappc9) cause autosomal recessive intellectual disability and obesity by unknown mechanisms." (PMID 38889014, 2024). "Moreover, abnormal epigenetic modification of the Trappc9 gene is associated with obesity in humans." (PMID 38889014, 2024). "These human-related studies define Trappc9 as a risk factor for obesity." (PMID 38889014, 2024). "While the Trappc9 syndrome is extremely rare, Trappc9 variations may contribute significantly to the prevalence of obesity based on the following features of Trappc9 pathogenic mutations." (PMID 38889014, 2024). "These human studies define Trappc9 as a risk factor for obesity." (PMID 38889014, 2024). "Obesity is frequently seen in patients with Trappc9 mutations." (PMID 38889014, 2024). "Trappc9-deficient mice develop phenotypes resembling pathological changes in humans and appear overweight shortly after weaning, and thus are useful for studying the pathogenesis of obesity." (PMID 35563289, 2022). "Even so, if conclusions from our mouse model can be extended, heterozygous carriers of the maternal mutant allele may show subclinical TRAPPC9 related phenotypes, including reduction in brain size, cognitive behavior and obesity, whereas carriers inheriting the paternal mutant allele may not." (PMID 32877400, 2020). "While we suggest altered dopamine transmission in the brain to be a key contributor, it is not clear to us in which brain region(s) dopamine transmission alteration plays a dominant role in the onset of obesity in Trappc9-KO mice." (PMID 38889014, 2024).
Obesity (continued). "It is also necessary for future studies to determine what role(s) ASC dysfunction plays in the development of obesity in Trappc9-KO mice." (PMID 38889014, 2024). "Our studies showed that Trappc9-KO mice presented with systemic glucose homeostatic disturbances, obesity, and NAFLD." (PMID 38889014, 2024). "First of all, our study only examined the contribution of dopamine transmission to the development of obesity in Trappc9-KO mice." (PMID 38889014, 2024). "Together, our data suggest that chronic treatment with drugs acting on dopamine receptors blunts the development of obesity and NAFLD in Trappc9-deficient mice." (PMID 38889014, 2024). "The combination of increased body weight and fat mass in female Trappc9-/- mice indicate an obesity phenotype similar to that observed in over half of TRAPPC9 deficient patients." (PMID 32877400, 2020). "It is not clear whether this divergence is related to the sex difference in time of onset of obesity and severity of phenotypes between female and male Trappc9-KO mice." (PMID 38889014, 2024). "In this regard, the effect of SCH23390 and quinpirole on glucose metabolism and obesity onset in Trappc9-KO mice might be achieved through actions in peripheral tissues." (PMID 38889014, 2024). "We then assessed whether chronic treatment combining SCH23390 and quinpirole prevented the development of obesity or NAFLD in Trappc9-KO mice." (PMID 38889014, 2024). "Human studies have suggested Trappc9 to be a risk factor for obesity and NAFLD, but the relevant mechanism is not clear." (PMID 38889014, 2024). "Hence, metabolic disturbance and obesity onset in Trappc9-KO mice most likely involve dysfunction of TRAPPII." (PMID 38889014, 2024). "Genome-wide analyses uncover differential methylation of the Trappc9 gene in children with severe obesity as well as in women with a high body mass index and link Trappc9 to nonalcoholic fatty liver disease (NAFLD), the most common liver disease frequently associated with obesity." (PMID 38889014, 2024). "Genome-wide association studies link Trappc9 to NAFLD, a common comorbidity of obesity." (PMID 38889014, 2024). "As maternal Trappc9 knock-out mice (Trappc9m-/p+) retain 30% brain Trappc9 expression versus 70% in paternal Trappc9 knock-out mice (Trappc9m-/p+) mice, the obesity phenotype positively correlates with the degree of Trappc9 depletion and therefore with Trappc9 allelic-biased expression in the brain." (PMID 32877400, 2020). "Nonsense mutations in TRAPPC9 have been reported in a total of 5 individuals with non-syndromic intellectual dysability from the Middle East, although brain abnormalities and obesity were described in only a few." (PMID 32928283, 2020). "In this regard, the development of obesity caused by Trappc9 mutations may involve a function independent of its association with TRAPPII." (PMID 38889014, 2024). "As the treatment combining DRD1 antagonist SCH23390 and DRD2 agonist quinpirole is effective in ameliorating deficits associated with multiple behaviors in Trappc9-KO mice, we reasoned that this treatment might also be beneficial in controlling obesity or NAFLD in Trappc9-KO mice." (PMID 38889014, 2024). "Hence, obesity onset in Trappc9-KO mice and the beneficial effects of quinpirole may involve functional change associated with astrocytes." (PMID 38889014, 2024). "However, patients bearing mutations of Trappc2, Trappc2l, Trappc4, Trappc6A/B, or Trappc10 do not develop obesity as patients with Trappc9 mutations do." (PMID 38889014, 2024). "However, the Trappc9 homozygous knockout mice lost weight during the acclimatisation periods when singly housed, making it difficult to draw conclusion about the drivers of the obesity phenotype." (PMID 32877400, 2020). "Chronic pharmacologic manipulation of dopamine transmission restored systemic glucose homeostasis and relieved obesity and NAFLD in Trappc9-KO mice." (PMID 38889014, 2024).
Obesity (continued). "The effectiveness of SCH23390 and quinpirole in relieving obesity and NAFLD in Trappc9-KO mice indicates that when ligands are sufficiently available, DRD1- or DRD2-containing neurons as well as their effector cells in Trappc9-KO mice function normally." (PMID 38889014, 2024). "As Trappc9 imprinting occurs specifically in the brain and not in other tissues, we reason that this parent-of-origin dependent obesity phenotype is most likely to be driven by disruption of the regulatory pathways in the brain." (PMID 32877400, 2020). "However, it is not clear how Trappc9 genetic variations trigger the development of obesity and NAFLD." (PMID 38889014, 2024).
developmental delay (9 papers, 2018 to 2025). "The study revealed that compound heterozygous TRAPPC9 gene variants cause developmental delay in a Chinese girl." (PMID 39184350, 2024). "Tissues from these patients do not appear to have been evaluated for the accumulation of lysosomal storage bodies, but in cells cultured from a subject with a homozygous TRAPPC9 missense variant and severe developmental delay, intracellular vesicular trafficking was impaired." (PMID 41300827, 2025). "Among 43 reported cases with mutations in TRAPPC9, all (100%) showed ID and developmental delay." (PMID 33719327, 2021). "According to the ACMG criteria, both variants detected in TRAPPC9 were classified as “likely pathogenic” and that parents who carries TRAPPC9 gene variant, but exhibit no developmental delays, suggests a recessive genetic mode for the proband." (PMID 39184350, 2024). "Furthermore, our findings expand the genotype spectrum of the TRAPPC9 gene, and provide more comprehensive information regarding genetic counseling for children experiencing developmental delay." (PMID 39184350, 2024).
mastitis (6 papers, 2015 to 2024). Inflammation of breast tissue during lactation or postpartum due to an obstructed duct or infection. "The associations of polymorphisms in CD4 and TRAPPC9 genes with milk production and mastitis resistance traits have been documented in previous reports." (PMID 36213405, 2022). "Keeping in view the importance of the SNP Chip from various published studies we used this technique in the present study to validate the role of the significant variants from our previous studies in CD4 and TRAPPC9 genes for production and mastitis resistance traits." (PMID 36213405, 2022). "TRAPPC9 is a candidate gene for the regulation of susceptibility to mastitis in Holsteins." (PMID 33391332, 2020). "In general, the present study using a newly designed CCSC-I for genotyping to validate the association of SNPs in TRAPPC9 and CD4 genes with milk production and mastitis resistance traits." (PMID 36213405, 2022). "The elevated level of TRAPPC9 gene enhances the activity of NF-κB signaling during mastitis development in dairy cattle." (PMID 36213405, 2022). "In previous genome-wide association studies (GWAS), a number of candidate genes (TRAPPC9, mTORC1, JAK2 and STAT5A) were observed to be associated with mastitis-related traits such as SCC." (PMID 32944235, 2020). "TRAPPC9 and ARHGAP39 genes reveal the two novel candidate genes associated with mastitis resistant traits in dairy cattle." (PMID 26370837, 2015). "Two genes (TRAPPC9 and ARHGAP39) identified by significant SNPs indicate that they are important candidate genes associated with mastitis-related traits." (PMID 26370837, 2015). "Furthermore, Mac-T cells treated with lipopolysaccharide and lipoteichoic acid showed significant downregulation of the TRAPPC9 gene in the mastitis group compared with the control group." (PMID 39045327, 2024). "Increases in TRAPPC9 boost methicillin NF-κB signaling during mastitis in dairy cattle." (PMID 39045327, 2024). "A comparison of the two groups revealed that TRAPPC9 methylation was higher in the mastitis group than in the control group, while TRAPPC9 gene expression was significantly lower in the low-SCC group (the control group) than in the high-SCC group (the mastitis group), indicating an opposite trend." (PMID 39045327, 2024). "Similarly, our in our previous study by using transcriptomic screening, we reported that TRAPPC9 gene was significantly associated with milk SCC and bovine mastitis susceptibility." (PMID 36213405, 2022). "In the present study, the polymorphisms in TRAPPC9 and CD4 genes that cause variation in the economic and health traits (milk production and mastitis resistance phenotypic traits) were selected from our previous studies and analyzed for validation in a new and larger population by using CCSC-I." (PMID 36213405, 2022). "For this purpose, these SNPs in TRAPPC9 and CD4 genes were detected by a new technique, i.e., Chinese Cow's SNPs Chip-I (CCSC-I) and genotyped in a different and a bit larger Chinese Holsteins population to explore their association with mastitis resistance and milk production phenotypic traits." (PMID 36213405, 2022). "RT-qRCR analysis showed that the mastitis group had significantly reduced expression of CD4 and TRAPPC9 genes compared to the control group (p < 0.05)." (PMID 39045327, 2024). "It was found that the expression of TRAPPC9 and CD4 genes was reduced in cows with mastitis, with the expression of TRAPPC9 induced by inflammation showing the same trend." (PMID 39045327, 2024). "Three SNPs in TRAPPC9 and one SNP from CD4 gene were screened through CCSC-I and genotyped in a total of 312 (156: Mastitis, 156: Healthy) Chinese Holstein population." (PMID 36213405, 2022). "TRAPPC9 and ARHGAP39 genes (each contains three significant SNPs on genome level) identified by MMRA can be considered potential candidate genes for mastitis-related traits." (PMID 26370837, 2015).
mastitis (continued). "The RT-qPCR results showed that both the TRAPPC9 and CD4 genes were expressed in the blood of cattle in the healthy and mastitis groups, and the expression levels of both genes were significantly higher in cows from the control group than those from the mastitis group (p < 0.05)." (PMID 39045327, 2024). "Altogether, our findings suggested that the SNPs of TRAPPC9 and CD4 genes could be useful genetic markers in selection for milk protein improvement and mastitis resistance phenotypic traits in dairy cattle." (PMID 36213405, 2022). "The present study was designed to evaluate the association of polymorphisms in bovine trafficking protein particle complex subunit 9 (TRAPPC9) and cluster of differentiation 4 (CD4) genes with milk production and mastitis resistance phenotypic traits in a different cattle population." (PMID 36213405, 2022). "The results verify that the documented SNPs in both genes (TRAPPC9 and CD4) could be considered as powerful genetic markers against bovine mastitis resistance." (PMID 36213405, 2022).
autism (5 papers, 2019 to 2025). Persistent deficits in social interaction and communication and interaction as well as a markedly restricted repertoire of activity and interest as well as repetitive patterns of behavior. "This may be a common circumstance—TRAPPC9 deficiency can masquerade as a complex and severe case of autism, causing its incidence to be highly underreported." (PMID 32162493, 2020). "Together this study provides evidence that clinical manifestations of TRAPPC9 mutations as seen in our patients with ID and autism may be broader than previous case reports have indicated." (PMID 30853973, 2019).
autosomal recessive intellectual disability (5 papers, 2014 to 2025). "Pathogenic mutations in TRAPPC9 are associated with autosomal recessive Intellectual Disability (ID), a major public health issue that affects about 1–3% of children worldwide." (PMID 33513295, 2021).
autism spectrum disorder (3 papers, 2020 to 2021). A spectrum of developmental disorders that includes autism, and Asperger syndrome. "In this case, an 18‐month‐old was diagnosed with an autism spectrum disorder and later found to also have TRAPPC9 deficiency/ IDT13." (PMID 32162493, 2020).
autosomal recessive mental retardation 13 (2 papers, 2024). "The TRAPPC9 gene, also known as NIBP (NIK-and-IKK2-binding protein) or MRT13 (autosomal recessive mental retardation 13), plays a pivotal role in neurodevelopment." (PMID 39184350, 2024).
cognitive defects (2 papers, 2020 to 2021). "Interestingly, TRAPPC9 (Trafficking Protein Particle Complex Subunit 9) is also implicated in vesicular transport and has similarly been linked to cognitive impairment." (PMID 34440432, 2021).
colon cancer (2 papers, 2015 to 2023). "This has been reported to be important in the trafficking and signaling pathways in health and disease in humans, where mutations in TRAPPC9 are linked to a form of mental retardation, breast and colon cancer, and liver diseases." (PMID 37308718, 2023). "Our understanding of NIBP/TRAPPC9 functions in cancer particularly in breast/colon cancer from the present study proposes that targeting NIBP/TRAPPC9 should witness a novel strategy for clinical diagnosis and therapeutic intervention to better identify and treat cancer patients." (PMID 25704885, 2015).
psoriasis (2 papers, 2022 to 2023). An autoimmune condition characterized by red, well-delineated plaques with silvery scales that are usually on the extensor surfaces and scalp. "However, there is not enough evidence for CFDP1, TRAPPC9, HSD17B7, and KIAA0415’s effects on psoriasis and neutrophils." (PMID 36569916, 2022).
abnormal glucose tolerance (1 paper, 2023). An abnormal resistance to glucose, i.e., a reduction in the ability to maintain glucose levels in the blood stream within normal limits following oral or intravenous administration of glucose. "After adjustment for maternal pregestational BMI, age, and gestational weight gain, a significant difference in methylation was observed at CpG sites in LINC00917 and TRAPPC9, which encodes trafficking protein particle complex subunit 9, in the women with abnormal glucose tolerance." (PMID 37047019, 2023).
cleft lip (1 paper, 2019). Congenital defect in the upper lip where the maxillary prominence fails to merge with the merged medial nasal prominences. "Patients in this study also show autistic feature and cleft lip which have been reported in very rare cases with TRAPPC9 mutations, suggesting a broader spectrum of clinical manifestations of TRAPPC9 mutations as seen in our patients, compared to previous case reports." (PMID 30853973, 2019).
dyslipidemia (1 paper, 2024). "In this study, we found that the ablation of Trappc9 resulted in disruption of systemic glucose homeostasis, which was associated with hyperinsulinemia, hyperleptinemia, hyperprolactinemia, dyslipidemia, adipocyte hypertrophy, and glucose metabolism reprogramming and lipid accumulation in the liver." (PMID 38889014, 2024).
glucose metabolism disorders (1 paper, 2024). "In GDM patients, LINC00917 and TRAPPC9 methylation levels were found to be useful indicators for identifying early glucose metabolism disorders four years after delivery." (PMID 39273309, 2024).
Hyperglycemia (1 paper, 2024). An increased concentration of glucose in the blood. "Hyperglycemia was detectable in Trappc9-KO mice at age 1 month and persisted thereafter." (PMID 38889014, 2024). "To challenge this idea, we first examined whether the treatment with SCH23390 and quinpirole mitigated hyperglycemia, hyperinsulinemia, and hyperprolactinemia in Trappc9-KO mice, as dopamine transmission modulates glucose homeostasis and inhibits prolactin and insulin secretion." (PMID 38889014, 2024).
Hyperinsulinemia (1 paper, 2024). An increased concentration of insulin in the blood. "The SCH23390 and quinpirole treatment also effectively corrected the hyperinsulinemia and hyperprolactinemia in Trappc9-KO mice and resulted in corresponding changes in brain levels of cAMP, indicating their actions in the brain." (PMID 38889014, 2024).